CD4 (CD4 molecule)
Diseases named in the same sentence as CD4 in open-access papers (continued):
Sharing a sentence is not in itself a finding about the gene and the disease.
tumor (continued). "During the cancer treatment process, tumour cells may escape immune cell attention, partly by tricking CD4+ T cells or by Treg cell inhibition of CD4+ T cells." (PMID 38158643, 2024). "To better understand the effect of Parp7 loss on T cell tumour infiltration, we also used a dedicated spectral flow cytometry panel capable of differentiating cancer-relevant T cell subpopulations including cytotoxic (CD8), helper (CD4), and TCRγδ T cells." (PMID 39867896, 2024). "This suggests that SFB-specific pro-inflammatory CD4+ T cells in the tumor may contribute to altering the tumor microenvironment, making it more responsive to anti-PD-1 therapy." (PMID 39185202, 2024). "According to the current evidence, CD4 T-cells are vital parts of the tumor immunity." (PMID 38308298, 2024). "We speculate that differences in the tumor subtypes of CD4 + cells may explain the variability observed among these studies, and suggests that analyzing the prognostic value of specific CD4 + T cell subsets may be of value." (PMID 38926643, 2024). "Additionally, CD4 memory‐quiescent T cells play a crucial role in defending against tumours by regulating the activity of other immune cells, such as CD8+ T cells and natural killer cells." (PMID 39031800, 2024). "Moreover, m6A regulatory enzymes, especially writers and erasers, influence the proliferation and infiltration of CD4+ T cells in the tumor immune microenvironment." (PMID 38696324, 2024). "Besides, a series of studies have found that the number of CD8+ T cells or the ratio of CD8+/CD4+ T cells in the tumor microenvironment are correlated with ICIs outcomes and serve as positive predictors of immunotherapy." (PMID 38236288, 2024). "Tumors may utilize regulatory T-cells (Treg) (CD4/CD25/FOXP3) to create favorable conditions for their development by suppressing the tumor-specific immune response." (PMID 38672662, 2024). "Additionally, the interaction between TCR+ Macrophages and CD4+ T cells was most pronounced in tumor tissues from responsive patients, whereas that between TREM2+ Macrophages and CD4+ T cells was more intimate in tumor tissues from non-responsive patients." (PMID 38948071, 2024). "In addition, treatment with 8 Gy x 3 fractions with CTLA-4 blockade increases tumor-infiltrating CD4+ and CD8+ lymphocytes." (PMID 38778925, 2024). "BiTEs can also redirect CD4+CD25+ Treg cells to tumor cells since these lymphocytes express CD3." (PMID 38339258, 2024). "cDC2 has also been shown to drive protective anti-tumor CD4 T cell immunity." (PMID 39372416, 2024). "Also, CD4+ Th1 cells promote anti-tumor responses by secreting cytokines important for CD8+ T cell proliferation, macrophage recruitment, and activation." (PMID 38672372, 2024). "Furthermore, the production of cytokines by CD4+ T lymphocytes enables indirect inhibition of tumor growth." (PMID 39050844, 2024). "Importantly, MIF is known to promote tumor-associated immune cell evasion by inhibiting DC migration, maturation, and antigen presentation, which helps the development of anti-tumor CD4+ and CD8+ effector T cells." (PMID 38730725, 2024). "(b) The proportions of tumor-infiltrating CD4+ and CD8+ T cells in different treatment groups." (PMID 38747577, 2024). "Moreover, patients with high tumor CD4+ and CD8+ T cell infiltration survived significantly longer compared to patients with low tumor CD4+ and CD8+ T cell infiltration (p < 0.0001 and p = 0.011, respectively)." (PMID 38841570, 2024). "Interestingly, Pearson coefficients showed that the degree of correlation between tumor SUVmax of 68Ga-FAPI and tumor-infiltrated CD8+ or CD4+ cells was comparable to the correlation between SUVmax of 68Ga-FAPI PET/CT and the expression of FAP-α." (PMID 38175716, 2024). "Furthermore, CD4+ T cells were more numerous than CD8+ cells in the tumor core of PMs, a finding that was confirmed in our study." (PMID 38384469, 2024).
tumor (continued). "The TIME of shTFEB tumors was more heterogeneous in composition upon PT treatment, including – among the differentially detected populations - anti-tumor (CD4+T-helper lymphocytes, Vγ9Vδ2 T-lymphocytes and natural killer - NK) cells, as well as pro-tumor (Treg and Th17 T-lymphocytes) cells." (PMID 39107857, 2024). "Importantly, the combination treatment also induced more tumor infiltration of immune cells, such as CD4+ T cells, in treated tumor specimens." (PMID 39007268, 2024). "HRD tumors are enriched with immunogenic epithelial cells, FGFR1+PDGFRβ+ myCAFs, M1 macrophages, tumor reactive CD8+/CD4+ Tregs, whereas HRP tumors are enriched with HDAC1‐expressing epithelial cells, indolent CAFs, M2 macrophages, and bystander CD4+/CD8+ T cells." (PMID 39136172, 2024). "It was already well known that CD4+ T cell plays a vital role in anti-tumor effector cells." (PMID 39749326, 2024). "Notably, tumors with high PCDI exhibited reduced infiltration of anti-tumor immune cells, including B cells, CD4+ T cells, and CD8+ T cells, compared to tumors with low PCDI." (PMID 38409471, 2024). "In view of the existing literature, this supports the hypothesis that a higher number of CD4+ T cells and a low number of Tregs seems to be a promising constellation for local tumor control." (PMID 39410037, 2024). "Conversely, by producing IL-4, -5, and -13, Th2-polarized CD4+ T cells may be involved in the downregulation of T cell-mediated cytotoxicity and in the induction of a tumor-promoting response." (PMID 38891095, 2024). "TIGIT contributes to tumor immune evasion through various immunity mechanisms, including inhibiting NK cell-mediated cytotoxicity, suppressing T-cell proliferation, restricting CD8+ T cell activation in the TME, and promoting inflammatory CD4+ T cell responses to impede tumor apoptosis." (PMID 38627681, 2024). "Importantly, the WT1 helper peptide can significantly contribute to tumor eradication not only through helper CD4+ T cells but also WT1-specific CD8+ CTLs in antitumor immunity." (PMID 38336778, 2024). "Moreover, the distance between CD4+Tregs (P < 0.001) or CD8+Tregs (P = 0.027) to tumor cells was longer in IM than in TC." (PMID 39093404, 2024). "A subset of CD4+ T cells expressing CD39 has also been shown to exhibit tumor reactivity." (PMID 38335302, 2024). "These may include naïve T cells, innate immune cells, or cells that have acquired specific immunity, including CD8+ cytotoxic T cells as well as CD4+ effectors sensitized to tumor antigens." (PMID 39165679, 2024). "Furthermore, DCs can activate CD4+ T cells and CD 8+ T cells via the presentation of tumor antigens and MHC‐II and MHC‐I, respectively, and thus, initiate the tumor‐specific adaptive immune response." (PMID 39463159, 2024). "The PD‐1+TCF1+CD8+ CD4+ T cells, first reported here according to our knowledge, might comprise a novel class of super anti‐tumor T cells." (PMID 39225354, 2024). "After inoculation with tumor cells, the proportions of CD4+ Tcm, CD4+ Tem, CD8+ Tcm, and CD8+ Tem cells in the spleen and lymph nodes in all groups mice increased with different degrees, and the proportions of CD8+ T cells and NK cells in the spleen were also increased." (PMID 38439023, 2024). "Molecular pathways underlying T-cell exhaustion have been defined for CD8+ cytotoxic T cells, but which factors drive exhaustion in CD4+ T cells, that are also required for an effective immune response against a tumor or infection, remains unclear." (PMID 39689157, 2024). "However, injected antibodies during the combined therapy caused depletion of CD4+ and CD8+ lymphocytes which allowed the elimination of tumor growth." (PMID 38892394, 2024). "Likewise, the populations of tumor-infiltrating CD4+ T cells (CD3+CD4+CD8−), crucial for regulating adaptive immunities, were also significantly elevated in “BC@Z-M + L” group compared to other groups." (PMID 39613774, 2024).
tumor (continued). "Furthermore, the microenvironment of bone metastatic cancer also attracts other T cell subtypes, such as Tregs and other CD4+ T cells, which can support tumor growth and metastasis." (PMID 38464516, 2024). "However, XBP1, a transcription factor of IRE1α-XBP1 signalling, inhibits the CD4+ T-cell-mediated immune response and promotes tumour progression." (PMID 38297380, 2024). "SCFAs increase tumor-killing CD4+ and CD8+ T cells and reduce T-regs." (PMID 39022585, 2024). "We found that, consistent with a higher targeting of immune pathways in females, various immune cell proportions including natural killer cells, CD4 + naive T cells, myeloid dendritic cells, and B cells were more highly targeted in female tumor samples than male tumor samples." (PMID 39107837, 2024). "CD4+Th cells can be further divided into anti-tumor Th1 and pro-tumor Th2." (PMID 39744013, 2024). "CD4‐positive T cells and tumoricidal myeloid cells induce remote inflammatory cell death, which indirectly eliminates interferon‐unresponsive and MHC‐deficient tumours." (PMID 39639610, 2024). "While HA15 treatment led to substantially reduction of Foxp3+CD4+ Tregs in TME, either the deficiency of IRE1α or XBP1 in tumor cells could partially reverse this alteration." (PMID 38291473, 2024). "However, we found that treatment with RUX alone, and in combination with PAC, decreased the frequency of intratumoral GZMB+CD8+ and GZMB+CD4+ cells, which suggests a switch to a less active, tumor-promoting immune environment." (PMID 38297352, 2024). "However, combined Phd2 deletion in myeloid and T-cells (LysM/CD4-Cre) led to a decreased tumour growth." (PMID 38509356, 2024). "Additionally, B-MFs contributed significantly to tumor progression by adopting immunosuppressive phenotypes and promoting cancer growth through the suppression of anti-tumor IFNγ+ CD4+ T cells and the induction of FoxP3+ Tregs." (PMID 39457693, 2024). "While targeting glucocorticoid-induced TNFR-related receptor (GITR) in Treg cells promoted CD4+ Tregs differentiation into CD4+ effector T cells, attenuated Treg cell-mediated suppression of anti-tumor immune response, and induced robust anti-tumor effector cells in GBM." (PMID 38907858, 2024). "Notably, regulating the differentiation of naïve CD4+ T cells into Th1, Th2, Th17, Th9, Th22, and Tregs is essential for eliminating immunosuppressive restrictions from the tumor environment and boosting effector T-cell activity." (PMID 38730319, 2024). "Their study in mouse tumor model revealed that VLP-OVAT effectively suppressed tumor growth through the promotion of CD4+, CD8+, and effector memory T cells (TEM cells) and the reduction of myeloid-derived suppressor cells (MDSCs) within tumor-infiltrating lymphocytes and spleenocytes." (PMID 38355548, 2024). "Altogether, these findings reveal a crucial role for the unique DC-Th-CTL interactions and their spatial positioning within the TME, where CD4+ T cells endow CD8+ T cells with the ability to determine the effectiveness of PD-1 antibody-mediated anti-tumor immunity." (PMID 39582060, 2024). "In contrast to CD8+ T-cells, we could not detect any differences in the proportion and activation of CD4+ T-cells in the tumour between infected and uninfected mice." (PMID 38271469, 2024). "Furthermore, the number of tumor-infiltrating CD4+ T cells was also significantly greater in TOFA-Th9 cells than in untreated Th9 cells." (PMID 39187636, 2024). "The two possible pathways for the recruitment of Tregs to the tumor microenvironment are either influenced by the priming of naive CD4+ T cells to differentiate into CD4+ CD25+ Tregs or by inducing the selective migration of Tregs via specific chemokine secretion." (PMID 38571964, 2024).
tumor (continued). "IL32 transcripts were present in all intratumoral Th subsets, though at different levels, with the highest expression in suppressive Treg followed by Th1 Teff, but also in circulating IFNγ+CD4+ Teff (Th1) reactive to the breast tumor antigen mammaglobulin (MAMI)." (PMID 39211051, 2024). "Likewise, the proportions of CD4+ T cells in both primary and distal tumor were markedly elevated in the mice treated with BC@Z-M + L, in contrast to the PBS + L control group." (PMID 39613774, 2024). "Our analysis using two distinct data sources indicates that B3GNT5 expression is inversely associated with CD8+ T lymphocytes, CD4+ T lymphocytes, and natural killer cells, which could help shed light on the connection between B3GNT5 and diverse tumor types." (PMID 39671359, 2024). "Importantly, MHC II molecule expression is crucial for initiating tumor immune responses by activating CD4+ T cells to target tumor cells." (PMID 39457014, 2024). "Moreover, the interactions between CD4+ T cells and various cells are crucial in tumor metastasis and represent a strategic approach for intervention in such processes." (PMID 39090094, 2024). "Targeting FAP-positive CAF in murine models has been shown to enhance anti-tumor immunity in several solid tumor models; a FAP-DNA vaccine induced CD8+ and CD4+ T-cells and synergised with other tumor antigen-specific DNA vaccines to enhance anti-tumor immunity." (PMID 38966131, 2024). "Although CD8+ T cells are well-documented for their direct tumor-killing abilities, our results suggest that NSG2 may amplify tumor immunogenicity, leading to increased CD4+ and CD8+ T cells populations." (PMID 39493764, 2024). "Moreover, the cytokine IL-7 promotes the differentiation of CD4+ T cells into Th9 cells with enhanced anti-tumour activity." (PMID 38675377, 2024). "Specifically, CD8+ T cells serve as effector cells engaged in eradication of tumor cells through recognition of tumor-associated antigens and neoantigens presented by MHC class I. Simultaneously, CD4+ T cells provide support to CD8+ T cells by secreting a diverse range of effector cytokines." (PMID 38779867, 2024). "The cognate assistance that CD4+ T helper cells provide to CD8+ T cells may also stimulate long-term immunological memory against the tumor." (PMID 38962577, 2024). "Interestingly, it appears that CD4+ T cell tumor infiltration can be important for effective immunotherapy." (PMID 38786066, 2024). "Additionally, KLRB1 expression was linked to tumor purity, stromal, immune, and estimate scores, the levels of immune cells including B cells, CD8+ T cells, and CD4+ T cells, and immune cell markers in LUAD." (PMID 38782996, 2024). "Simultaneously, a slight increase in the infiltration of CD4 + T cells, CD8 + T cells, CD56 + NK cells, TAMs, and tumor-associated neutrophils (TANs) could be noted, with a relatively low change ratio." (PMID 38926205, 2024). "These increased intra-tumoral CD4+/CD8+ cells might be the final effectors contributing to tumor eradication under the sequential activation from anti-PD-1 blockade." (PMID 38448521, 2024). "The H3K27M-reactive TCRs in the CSF were identified as central memory CD4+ T cells, which have previously been shown to be superior in controlling tumor growth both in vitro and in vivo because of their increased cytokine secretion and prolonged persistence relative to effector T cells." (PMID 38306431, 2024). "The underlying mechanism of the combined and synergistic effects of the 3D scaffold in chemo-assisted immunotherapy was based on the upregulation of cytotoxic T-lymphocytes’ (CTLs) tumor effects, as evidenced by the significantly increased expression levels of activated CD4+ and CD8+ T cells." (PMID 38791452, 2024).
tumor (continued). "We found that compared to the LPSG, the HPSG showed a significant positive correlation with anti-tumor cells, such as type 1 and 17 T helper cells, Natural killer cells, activated dendritic cells, Natural killer T cells, Activated CD4+, CD8 + T cells, and activated B cells." (PMID 38758862, 2024). "Inhibition of PI3K in vitro resulted in decreased proliferation and increased cell death in primary CD4+ PTCL cells harvested from patient lymph nodes, further illustrating the reliance of canine CD4+ PTCL on PI3K/AKT/mTOR signaling for tumor cell proliferation and survival." (PMID 38166662, 2024). "CD8+ Cytotoxic T cells induce cell death in virus- or tumor-infected cells, and compared to CD4+ T cells, CD8+ T cells age faster—or progress to the terminally differentiated state faster, a process thought to be driven by the reactivation of latent herpesviruses." (PMID 39006475, 2024). "Additionally, a small cluster of TCR135-transduced CD4+ T cells differentiated into Tregs within the tumor microenvironment." (PMID 38412034, 2024). "Together, these results indicate that STAT6 mutant rrDLBCL cells remodel their tumor microenvironment (TME) via the secretion of the chemokine CCL17 to attract CD4+ T-cells, although the subtype of CD4+ T-cells which were recruited were not determined in this study." (PMID 38285120, 2024). "Because CD20+ B cells and CD4+ CD38+ T cells promote cytotoxic T cells for killing tumor cells, the observed distribution pattern indicates that FOXP3+ Tregs and CD66+ neutrophils might synergistically attenuate this process." (PMID 38674427, 2024). "This suggested that ARF5 might participate in the infiltration process of immune cells by promoting the activation of CD4+T cells, promoting immune escape of tumor cells, thereby promoting the progression of HCC and leading to malignant prognosis." (PMID 38617932, 2024). "Therefore, we subsequently depleted CD8+ or CD4+ T-cells in tumour-bearing mice during IAV infection to test which of these cell types are the driver of tumour growth control in this setting." (PMID 38271469, 2024). "Taken together, these considerations have guided us to investigate the possibility that an optimal stimulation of the tumor specific CD4+ TH cells could better activate the cascade of events leading to an efficient anti-tumor therapy in OSCC." (PMID 39035008, 2024). "Furthermore, TIGIT-expressing CD4+ T cells represent a tumor-supportive T cell subset in CLL and TIGIT blockade can restore CD8+ T-cell immunity against multiple myeloma (MM)." (PMID 38229100, 2024). "In summary, our findings suggest that IFN-I signature enrichment is a distinguishing feature of tumor-infiltrating, tumor-reactive Ki67+ CXCL13+CD4+ T cells that license cDC1s for the induction of antitumor CTL activity in the TME, which potentially leads to a favorable clinical outcome." (PMID 38383773, 2024). "As a mechanosensory protein, PIEZO1 may respond to external forces and participate in the modulation of the TME and cytoskeletal reorganization to establish an environment that physically inhibits CD8+ and CD4+ T cells from penetrating the tumor." (PMID 38398074, 2024). "This expression profile facilitates stronger interactions between M2 macrophages and CD4 + T cells, including Tregs, suggesting that M2 macrophages play a role in recruiting or activating CD4 + T cells and Tregs, thereby aiding tumor cells in evading the immune response." (PMID 39068459, 2024). "iNKT cells can also secrete IL-12 which activates anti-tumor CD4+ and CD8+ T cells." (PMID 38993780, 2024). "However, IL-18 also displays anti-tumor ability to inhibit the growth and metastasis of many types of tumor cells by activating the immune response of CD4 + T cells and/or NK cells in the TME." (PMID 38553639, 2024).